TNF (tumor necrosis factor)
Diseases named in the same sentence as TNF in open-access papers (continued):
Sharing a sentence is not in itself a finding about the gene and the disease.
triple-negative breast carcinoma (continued). "Considering its role as a c-Jun-regulated antiapoptotic gene, apoptosis was induced by Ninj1 downregulation in triple-negative breast cancer cells and further accelerated by TNF-α, whereas Ninj1 overexpression ameliorated TNF-α-induced apoptosis in c-Jun knockdown cells." (PMID 30700695, 2019). "Moreover, CRISPR/Cas9-mediated deletion of MIB1 and MIB2 also sensitized the triple-negative breast cancer cell line MDA-MB-231 to TNF/TAK1i in a RIPK1-dependent manner." (PMID 29642005, 2018). "Finally, TNF-α gene knockout has shown to induce apoptosis and inhibit cell proliferation in the triple negative breast cancer cell line Hs578T." (PMID 29202842, 2017). "Thus, there is significant interest in understanding the molecular signaling pathways that connect TNF-α with the aggressive behavior of triple negative breast cancer." (PMID 23263670, 2012). "In addition, TNF-α could promote triple-negative breast cancer cell metastasis through targeting TNFR2-ERK1/2-EZH2 signaling." (PMID 37124061, 2023). "Thus, given the dynamic control of diverse chemokines as key trafficking molecules released by tumor cells in response to TNFα capable of driving LSP recruitment, here we investigated the effects of apigenin on TNFα mediated chemokine release in triple-negative breast cancer (TNBC) cells." (PMID 28441391, 2017). "In fact, it was shown that PsA-D attenuated NF-κB activation induced by lipopolysaccharide (LPS) and tumor necrosis factor-alpha (TNF-α) in both the human monocytic THP-1 cell line and the MDA-MB-231 triple-negative breast cancer (TNBC) cell line." (PMID 40559654, 2025). "Baicalin inhibits the protein expression of MMP9, TNF-α and JAK2 and their related signaling pathways in the treatment of triple-negative breast cancer." (PMID 40356970, 2025). "Such Birinapant-induced, endogenous TNFα- and TRAIL-dependent cell death has already been described for different tumor cells, among them also for triple negative breast cancer cells (TNBC)." (PMID 36158196, 2022). "In this review we summarize the recent findings on TNFα participation in luminal, HER2-positive and triple negative breast cancer progression and metastasis." (PMID 32391269, 2020). "To further investigate the mechanisms behind takinib + TNF treatment on cancer cell death, we performed apoptosis marker screens on MDA-MB-231, a triple negative breast cancer line." (PMID 32523651, 2020). "Tumor necrosis factor alpha (TNF-α) is a pro-inflammatory cytokine involved in the promotion and progression of cancer, including triple negative breast cancer cells." (PMID 23263670, 2012). "In triple-negative breast cancer, the JNK/c-Jun/TNF-α signaling axis promotes PD-L1 expression." (PMID 40092686, 2025). "miR-4649-3p has been identified as a tumor suppressor in triple-negative breast cancer by targeting PIP5K1C, an Akt activator, while miR-615 targets the NK group 2 (NKG2) family receptor or TNF-α from immune cells, leading to diminished cytotoxic activity against tumor cells." (PMID 38339019, 2024). "Similar to MMP9, CDKN1A/p21 expression is upregulated in triple-negative breast cancer following TNFα exposure, which is not observed in normal cells." (PMID 38139316, 2023). "Our model also could distinguish patients with a specific cancer subtype, triple-negative breast cancer (TNBC), which is known to be influenced by NFκB-regulated pathways downstream of TNF." (PMID 37475016, 2023). "In addition, PC3-M and C4–2B-M cells expressed significantly high levels of TNF mRNA and TNF-α protein compared to their parental cells (PC3–P and C4–2B–P) and the triple-negative breast cancer cell line, MDA-MB-231 that is known to make TNF-α." (PMID 37867861, 2023).
triple-negative breast carcinoma (continued). "Further GO and KEGG analysis showed that the activity of Zn{[CH3)3C]2Sal}22− against triple-negative breast cancer cells may be involved in the JAK-STAT3, HIF-1, and TNF signaling pathways." (PMID 35296801, 2022). "Furthermore, the triple negative breast cancer cell line MDA-MB-231 induced expression of IL-6, TNFα and MCP-1 in the presence of stimulated THP-CM (IL-6 induction 177-fold, TNFα induction nearly 10-fold and MCP-1 induction nearly 19-fold)." (PMID 28832545, 2017). "Interestingly, TNF-α downregulated Nischarin and stimulated the expression of both miRNAs in HER2 and triple negative breast cancer cell lines." (PMID 29202842, 2017). "miR-483-5p has also been found to have a carcinogenic role in triple-negative breast cancer in that it inhibits SCOS3 (suppressor of cytokine signaling 3) gene expression that may trigger the pathway of STAT3, NF-κB, and primary inflammatory cytokines such as TNF-α, IL-6, MCP-1, and IL-1β." (PMID 37298699, 2023). "It is noteworthy that irrespective of exogenous cytokine stimulation via LPS or TNFα, pseudopterosins are able to significantly reduce endogenous release of at least two cytokines in the MDA-MB-231 triple negative breast cancer cells (IL-6 1.2-fold, IL-8 1.4-fold, MCP-1 1.4-fold)." (PMID 28832545, 2017).
Erythema (58 papers, 2014 to 2026). Redness of the skin, caused by hyperemia of the capillaries in the lower layers of the skin. "Moreover, in vitro studies have shown that capsaicin exposure triggers TRPV1-mediated Ca2+ influx in keratinocytes, leading to the release of inflammatory cytokines such as IL-6, IL-8, and TNF-α, which are linked to erythema, capillary dilation, and pain." (PMID 40041491, 2025). "Moreover, the application of GL can effectively relieve UV radiation induced erythema and leathery skin, associated with the down-regulated expression of inflammatory cytokines (TNF-α, IL-6 and IL-10)." (PMID 33526759, 2021). "C. acnes inoculated subcutaneously into the back of the ears induce ear swelling, redness, and erythema, which are associated with the local and systemic production of TNF-α, IL-6, and IL-8 as well as the infiltration of CD45+Ly6G+ neutrophils and CD45+F4/80+ macrophages into the infected tissue." (PMID 34361921, 2021). "The main observation indicators included patient's skin recovery-related indicators (time to erythema disappearance and time to scab shedding) and levels of inflammatory factors [serum interleukin-6 (IL-6) and tumor necrosis factor alpha (TNF-α)]." (PMID 42164155, 2026). "Myr treatment significantly alleviated IMQ-induced erythema, scaling, and epidermal thickening, improved skin-barrier function, and reduced the expression of IL-6, IL-17A, and TNF-α." (PMID 41471291, 2025). "Preclinical research utilizing mouse models has demonstrated the efficacy of nano-TQ in reducing inflammation, erythema, scaling, epidermal thickness, and cytokine levels such as TNF-α and IL-17 in psoriatic lesions." (PMID 39188726, 2024). "The study assessed the effects of various concentrations of dapagliflozin ointment on levels of tumor necrosis factor-alpha (TNF-alpha), interleukin-8 (IL-8), IL-17, and IL-37, as well as on erythema, scaling, and epidermal thickness." (PMID 39044933, 2024). "ABT, APS, and ABPS all reduced the erythema of ear acne, decreased microcirculation in localized ear acne, and decreased serum levels of TNF-α and IL-1β in rats." (PMID 37159798, 2023). "Inflammatory cytokines, such as IL-1, IL-6, and tumor necrosis factor- (TNF-α), stimulate inflammatory cells (neutrophils and macrophages), increase vascular permeability, and cause swelling and erythema." (PMID 36619389, 2022). "The initial release of IL-1α and TNF-α starts a further cascade of pro-inflammatory chemo- and cytokines, resulting in inflammation and erythema of the skin." (PMID 35053737, 2022). "This includes the NFκB transcription system upon which induction by UV leads to an increase in the level of various inflammatory cytokines, including IL-6 and TNFα that enhance inflammatory responses such as erythema and sunburn." (PMID 33808148, 2021). "In contrast, TNF/Mel/SM resulted in all animals developing marked erythema and superficial desquamation, equating to grade III reactions." (PMID 32419365, 2020). "Our results showed that UV exposure induced erythema, edema, and epidermal hyperplasia of the mice skin, while upregulating the levels of IL-1β, IL-6, TNF-α, and IL-10 in mice skin significantly." (PMID 26903706, 2016). "On the other hand, in EM, infection or drug exposure leads to the excessive expression of inflammatory mediators, such as interferon-gamma (IFN-γ), tumor necrosis factor-alpha (TNF-α), perforin, and granzyme B, resulting in severe skin inflammation, erythema, and epidermal destruction." (PMID 40104458, 2025). "Furthermore, both formulations showed reduction in erythema, ear thickness and edema score, and significantly reduced the protein expression of IL-12 and TNF in the dinitroflurobenzene model." (PMID 36986611, 2023). "Moreover, the application of GL can effectively remiss UVB radiation induced skin erythema and leathery skin, via inhibiting the production of inflammatory cytokines such as TNF-α, IL-6, and IL-10." (PMID 33526759, 2021).
Erythema (continued). "Furthermore, in 3/16 (18.8%, 95% CI: 4.1–45.7%) patients receiving TNF-α inhibitors and in 0/32 (0%, 95% CI: 0–10.9%) controls the duration of erythema exceeded 100 days (p = 0.0324)." (PMID 31684103, 2019). "Indeed, the extent of erythema and swelling was reduced to levels observed in mice treated with a TNF inhibitor." (PMID 27511630, 2016). "The researchers observed that CO2 can decrease the production of IL-6 and TNFα in human keratinocytes and the 3D epidermis, thereby decreasing the formation of UVB-induced erythema in human skin." (PMID 39857811, 2025). "The suppression of TNF-α and IL-6 in CO2 treatments correlates with clinical observations of decreased erythema, reduced swelling, and improved granulation tissue formation." (PMID 39857811, 2025). "This cytokine activates nuclear factor kappa‐B (NF‐κB), escalating pro‐inflammatory responses like TNF‐α and PGE2, which manifest as erythema." (PMID 40952030, 2025). "Etanercept, a tumor necrosis factor-alpha (TNF-α) inhibitor, suppresses key inflammatory responses, masking classic CNF signs such as erythema, bullae, or crepitation, which are present in 70-80% of cases." (PMID 40821270, 2025). "Tumor necrosis factor-alpha (TNF-α) is a chief mediator that amplifies inflammatory responses in the dermis and epidermis, resulting in irAEs such as erythema and pruritus." (PMID 40271531, 2025). "It was noted that PPD induration/EC erythema compared with the control were enriched in DEPs involved mostly in the coagulation and complement cascades, NOD-like receptor signaling and TNF signaling." (PMID 38068935, 2023). "It was found that CO2 suppressed TNFα and IL-6 production in human keratinocytes and the 3D epidermis and attenuated UVB-induced erythema formation in human skin." (PMID 33431967, 2021). "Subsequently, erythema, scaling, and thickness of the dorsal skin were induced in the model group, and these symptoms were attenuated in the IMQ/anti-TNF-α group." (PMID 32280718, 2020). "Fatigue symptoms, erythema, and cytokine levels (IL-1β, IL-2, IL6, IL-8, TNF-α, and MCP-1) were registered at baseline, during treatment, and after radiotherapy completion." (PMID 24800238, 2014). "According to the results of this study, EEFR effectively prevented epidermal hyperplasia and hyperkeratosis in DNFB-treated mice by inhibiting the production of TNF-α, IFN-γ, IL-6, and MCP-1, and thus, ameliorated scaling, erythema, excoriation, and skin thickening." (PMID 37047066, 2023). "The IFN-γ level in PPD induration was found to be slightly higher than in EC erythema, but the differences in the levels of IFN-γ and TNF-α were not significant." (PMID 38068935, 2023). "PPD induration and EC erythema revealed upregulated expression of IFN-γ and TNF-α compared with the PBS group, while no increases were seen in IL-4 expression, thus indicating that Th1 cytokines were mainly expressed in PPD induration and EC erythema." (PMID 38068935, 2023). "Mild erythema observed postremoval resolved spontaneously,and no significant changes were noted in serum biomarkers such asC-reactive protein (CRP), immunoglobulin G (IgG), interleukin-1β(IL-1β), or tumor necrosis factor-α (TNF-α), confirmingthe absence of systemic inflammation or immune activation." (PMID 41018573, 2025).
chorioamnionitis (57 papers, 2006 to 2025). A morphologic finding indicating inflammation of the fetal sac membranes. "Increasing levels of infection-mediated pro-inflammatory cytokines, including TNF, IL-1β, IL-6, and IL-2, have been linked to chorioamnionitis and adverse pregnancy outcomes." (PMID 38877443, 2024). "Elevated levels of pro-inflammatory cytokines such as TNFα, IL-1, IL-12, IL-6, and IL-2 have been linked to chorioamnionitis and therefore elevated levels of these cytokines serve to identify potential pregnancy complications." (PMID 33123496, 2020). "Specifically, elevation of pro-inflammatory cytokines/chemokines such as IL-1β, Il-6, IL-8 and TNF-α within the AF and fetal membranes have been associated with preterm delivery and chorioamnionitis." (PMID 22253806, 2012). "Our analysis included inflammatory mediators reported to be associated with chorioamnionitis, preterm labor, and fetal inflammatory response syndrome such as IL-1α, IL-1β, IL-6, TNF-α, S100A8, and S100A9." (PMID 22952869, 2012). "Intra-amniotic infections, such as funisitis or chorioamnionitis, are associated with higher levels of inflammatory cytokines, such as tumor necrosis factor alpha (TNFα) and interleukins (IL), including IL-1beta (IL-1b), IL-6, and IL-8 in amniotic fluid, cord blood, and newborn blood samples." (PMID 35626879, 2022). "While pro-inflammatory cytokines are associated with inflammation during chorioamnionitis, pro-inflammatory cytokines downstream of NF-κB activation, such as TNFα, play an important role in uterine homeostasis and initiating critical events during the estrous cycle and pregnancy." (PMID 33123496, 2020). "This prevented us from analyzing whether the vaginal fluid IL-6 and TNF-α concentrations changed on the last day before labor, because there is a higher risk for the development of chorioamnionitis when there is a longer latency period in the rupture of the membranes." (PMID 33800521, 2021). "Elevated levels of cord blood proinflammatory cytokines (IL‐1β, TNFα, and IL-6) have also been associated with preterm birth, one of the most common causes of neonatal morbidity and mortality, as well as chorioamnionitis, brain white matter damage, and chronic lung disease in preterm infants." (PMID 20940111, 2011). "We performed targeted analyses utilising Random Forest Algorithm of the same eight cfRNA targets (IL1α, IL1β, IL6, IL8, IL10, IL18, CD14, TNFα) used in the chorioamnionitis study." (PMID 40464837, 2025). "In contrast, targeted analysis of IL8, IL10, IL18, TNFα in maternal plasma of the 2 d Sterile Chorioamnionitis Group animals improved predictive value with a mean AUC of 0.73 (95% CI 0.39–1) Sensitivity 100%, Specificity 71%, PPV 0.82, NPV 1.0." (PMID 40464837, 2025). "Chorioamnionitis triggers vascular remodeling via pro-inflammatory cytokines like interleukin-1 and TNF-alpha (tumor necrosis factor), resulting in PDA and contributing to persistent pulmonary hypertension in newborns." (PMID 40149646, 2025). "In in vitro studies, ureaplasma had similar upregulate effects in TNFα, IL-1β, IL-6 and IL-8, which were commonly associated with PROM or chorioamnionitis." (PMID 38570745, 2024). "We also investigated other pro-inflammatory cytokines involved in GBS-induced chorioamnionitis, including IL-6 and TNF-α." (PMID 35563368, 2022). "Various cytokines, such as IL-1, IL-6, IL-8, and tumour necrosis factor-α (TNFα), have been discovered to play a role in the pathogenesis of chorioamnionitis-induced foetal inflammation." (PMID 35453930, 2022). "Vaginally obtained amniotic fluids with IL-6, MMP-8, and TNF-α seem to be good predictors for chorioamnionitis in patients with preterm premature rupture of the membranes before 34 weeks of gestation." (PMID 33800521, 2021). "The vaginally obtained amniotic fluid IL-6, MMP-8, and TNF-α seem to be good predictors for chorioamnionitis of patients with preterm premature rupture of membranes before 34 weeks of gestation." (PMID 33800521, 2021).